CTLA4 (cytotoxic T-lymphocyte associated protein 4)
Diseases named in the same sentence as CTLA4 in open-access papers (continued):
Sharing a sentence is not in itself a finding about the gene and the disease.
melanoma (continued). "This information for samples from a cohort of 30 melanoma patients is paired with the response (responder or nonresponder, determined by immune-related response criteria or irRC) to immune checkpoint inhibitors (ICIs) involving anti-PD1, anti-CTLA4, or the combination of the two." (PMID 39677361, 2024). "MHC-II expression was observed in > 1% of melanoma cells in 55/181 (30%) patients, and correlated with IFN-γ and its mediated gene signature, which could predict the response to anti-PD-1 but not anti-CTLA-4 therapy." (PMID 32864131, 2020). "We implanted 2.5 × 104 B16-F10 melanoma cells on the right and left flanks and treated mice on days 3, 6, and 9 with ODN1826 at 30μg either intra-tumorally or systemically with or without concomitant anti-CTLA-4 (9H10) or anti-PD-1 either locally (10μg) or systemically (100μg/250μg)." (PMID 31771649, 2019). "However, anti-CTLA-4 (ipilimumab) plus gp100 peptide vaccine did not improve the OS, compared with anti-CTLA-4 alone (10.0 versus 10.1 months) in a phase III trial in advanced melanoma patients." (PMID 27847783, 2016). "Given these limitations, a randomized phase III trial in melanoma showed that combined inhibition of PD-1 and LAG-3 resulted in improved clinical outcomes, suggesting that targeting PD-1 and LAG-3, rather than PD-1 and CTLA-4, could be a safer and potentially more effective strategy in OCCC." (PMID 41383608, 2025).
metastatic melanoma (708 papers, 2009 to 2026). A melanoma that has spread from its primary site to another anatomic site. "Nowadays, therapeutic blockade of the immune checkpoint programmed cell death receptor 1 (PD-1) alone or in combination with targeting cytotoxic T-lymphocyte-associated protein-4 (CTLA-4) is standard-of-care treatment for metastatic melanoma." (PMID 41558811, 2026). "The current standard of care for patients with metastatic melanoma is a combined therapy with cytotoxic T-lymphocyte-associated protein-4 (CTLA-4) antibody ipilimumab and programmed cell death protein (PD-1) antibody nivolumab, with 5-year OS rates of 52%." (PMID 40940903, 2025). "Since the approval of cytotoxic T lymphocyte-associated protein 4 (CTLA-4) inhibitors for the treatment of metastatic melanoma in the United States in 2011, PD-1/L1 inhibitors have been used to treat over 20 other malignancies." (PMID 40038799, 2025). "A large body of evidence has reported several risk factors or predictive factors of CTLA-4 inhibitor-induced colitis, with the most evidence arising from studies on patients with advanced or metastatic malignant melanoma who received ipilimumab." (PMID 38539558, 2024). "In a study focused on metastatic melanoma, it was discovered that decreased CTLA-4 mRNA levels were associated with a worse prognosis." (PMID 38462628, 2024). "The use of PD-1 inhibitors, namely nivolumab and pembrolizumab, and the anti-CTLA-4 drug, ipilimumab, has been shown to be associated with a steady regression in malignancies, including metastatic melanoma." (PMID 38410760, 2024). "The first immune checkpoint inhibitor (ICI) is ipilimumab, which is an antibody for cytotoxic T lymphocyte-associated protein 4 (CTLA-4) and clinically effective in treating metastatic melanoma." (PMID 38164171, 2024). "Pretreatment serum levels of CXCL11 have been linked to poor overall survival in patients with metastatic melanoma treated with anti-CTLA-4 ICI therapy." (PMID 39736644, 2024). "The first ICI approved for the treatment of metastatic malignant melanoma was ipilimumab, an anti-CTLA-4 antibody which is associated with a median OS of 11.4 months (95% CI, 10.7 to 12.1 months) and a 3-year survival rate of 22% (95% CI, 20% to 24%)." (PMID 36979727, 2023). "Although tumor CTLA4 levels are associated with prognosis in patients with metastatic melanoma, tumor CTLA4 expression levels are dynamically regulated by various factors and are technically challenging to test." (PMID 37197667, 2023). "Our findings shed light on the mechanisms underlying the downregulation of CTLA4 in Treg cells in patients with metastatic melanoma." (PMID 37197667, 2023). "The results showed that downregulated CTLA4 expression was associated with worse OS in the Swedish dataset of metastatic melanoma patients (p = 0.0046), consistent with the observations in the TCGA dataset." (PMID 37197667, 2023). "To investigate further, we measured blood CTLA4 mRNA in 273 whole-blood samples from an Australian cohort and found that it was lower in metastatic melanoma than in healthy controls and associated with worse patient survival." (PMID 37197667, 2023). "In metastatic melanoma CTLA-4 and PD-1 antibody therapy caused a decrease in ctDNA when measured at 3 weeks and overall survival correlated with this decrease in ctDNA." (PMID 36735656, 2023). "The results from the AUS cohort confirm that lower blood CTLA4 levels are associated with worse prognosis in metastatic melanoma patients." (PMID 37197667, 2023). "A 65-year-old man received immune checkpoint inhibitors (ICIs), anti-CTLA-4 (cytotoxic T-lymphocyte-associated protein 4) and anti-PD-1 (programmed cell death 1) antibodies for aggravated metastatic malignant melanoma." (PMID 36894873, 2023).
metastatic melanoma (continued). "Since the approval of the cytotoxic T-lymphocyte associated protein-4 (CTLA-4) inhibitor ipilimumab for the treatment of patients with metastatic melanoma in 2011, immune checkpoint inhibitors (ICIs) have revolutionized the management of cancer patients." (PMID 37174104, 2023). "In recent years, the treatment of advanced tumors, especially metastatic melanoma, has been revolutionized by the use of immune checkpoint inhibitors (ICIs), including PD-1/PD-L1 inhibitors and cytotoxic T-lymphocyte-associated antigen 4 (CTLA-4)." (PMID 37175661, 2023). "Recent studies have shown that pre-treatment levels of CTLA4 expression in tumor samples are associated with clinical benefits from anti-CTLA-4 immunotherapy in metastatic melanoma patients." (PMID 37197667, 2023). "In the current study, we investigated the levels of CTLA4 mRNA expression and found that low levels of CTLA4 expression in both tumor tissue and blood cells are associated with poorer overall survival in patients with metastatic melanoma." (PMID 37197667, 2023). "Starting with the approval of anti-cytotoxic T lymphocyte-associated protein 4 (anti-CTLA-4) for advanced metastatic malignant melanoma in 2011, immune checkpoint inhibitors (ICIs) have since included antibodies against programmed cell death 1 (PD-1) as well." (PMID 36765835, 2023). "They further showed that increasing TA-HEC density and maturation in the TME is associated with a better anti-PD1/anti-CTLA-4 treatment response and survival rate in patients with metastatic melanoma." (PMID 36671443, 2022). "Systemic anti-cytotoxic T-lymphocyte-associated protein 4 (CTLA4) Ab was the first licensed ICI against advanced metastatic melanoma, and was then quickly followed by anti-programmed cell death ligand and protein 1 (PD-L1/PD-1) Abs." (PMID 36134952, 2022). "Immune checkpoint inhibition therapies, targeting cytotoxic T-lymphocyte-associated Protein 4 (CTLA-4) or programmed cell death protein 1 (PD-1) have ameliorated outcomes of several different cancer types including metastatic melanoma and others." (PMID 36700232, 2022). "In fact, antagonists of immune checkpoint molecules such as cytotoxic T-lymphocyte-associated protein 4 (CTLA-4) and programmed cell death protein 1 (PD-1) have been used for the treatment of unresectable or metastatic melanoma." (PMID 36338651, 2022). "This peptide has been engineered to bind to cytotoxic T Lymphocyte-associated antigen-4 (CTLA-4) which happens to be a target in the treatment of metastatic melanoma." (PMID 36501311, 2022). "Immune checkpoint inhibitors (ICI) targeting programmed death-1 (PD-1), its ligand PD-L1, and cytotoxic T lymphocyte-associated antigen 4 (CTLA-4) have revolutionized the treatment of metastatic melanoma, leading to long-term remissions or cure." (PMID 35159386, 2022). "In metastatic melanoma, Faecalibacterium enrichment is associated with a good clinical response to ipilimumab (an immune checkpoint inhibitor targeting CTLA-4)." (PMID 35585879, 2022). "High levels of butyrate and propionate are further associated with resistance to CTLA4 blockade in metastatic melanoma patients, and butyrate supplementation reduced anti-CTLA4-induced DC maturation and CD8+ T cell priming in a syngeneic tumor mouse model." (PMID 34413487, 2022). "In this paper we consider patients of NSCLC or metastatic melanoma who are treated with CTLA-4 inhibitor (ipilimumab), and thus are at risk of severe adverse events, such as permanent damage to a vital organ." (PMID 36355837, 2022). "Low baseline NLR levels were associated with prolonged PFS and OS in metastatic melanomas following treatment with ipilimumab (CTLA-4)." (PMID 36686795, 2022). "In this respect, the programmed death-1 (PD1) and cytotoxic T-lymphocyte associated antigen-4 (CTLA4) immune checkpoints are major resources against metastatic melanoma, as a standard treatment and in the adjuvant setting." (PMID 35203494, 2022).
metastatic melanoma (continued). "For example, CTLA-4 (Cytotoxic T-Lymphocyte Associated Protein 4) and PD-1/PD-L1 (Programed Death 1/Ligand-1)/inhibitors have greatly improved the poor prognosis of metastatic melanoma." (PMID 34307322, 2021). "This led to Food and Drug Administration (FDA) approval of ipilimumab (Yervoy), an anti-cytotoxic T lymphocyte associated protein-4 (anti-CTLA4) antibody, in 2011 for the treatment of newly diagnosed or previously treated unresectable/metastatic melanoma." (PMID 33810182, 2021). "Over the last decade, treatment of metastatic melanoma has profoundly improved due to the introduction of immune checkpoint inhibitors (ICI) against cytotoxic T-lymphocyte-associated protein 4 (CTLA4) and programmed cell death 1 (PD1)." (PMID 32929554, 2021). "The CTLA4 inhibitor ipilimumab is associated with durable survival benefits in patients with metastatic melanoma." (PMID 35008346, 2021). "High expression of cytotoxic T-lymphocyte-associated protein 4 (CTLA-4) was closely related to antigen-specific T cell dysfunction in metastatic melanoma." (PMID 33441929, 2021). "For example, the level of CTLA-4 always predicts the effect of ipilimumab therapy and the risk of developing irAEs in metastatic melanoma." (PMID 34367975, 2021). "In human metastatic melanoma, we found that the NK cell activation signature associates with longer overall survival and is predictive of anti-CTLA-4 (ipilimumab) response." (PMID 34376232, 2021). "Since the approval of the cytotoxic T-lymphocyte associated antigen-4 (CTLA-4) inhibitor ipilimumab for the treatment of metastatic melanoma in 2011, immune checkpoint inhibitors (ICPI) have become a cornerstone in the treatment of solid malignancies." (PMID 34449592, 2021). "The CII monoclonal antibodies approved to treat metastatic melanoma patients include ipilimumab (targeting cytotoxic T lymphocyte-associated antigen 4, CTLA-4), nivolumab and pembrolizumab (targeting programmed cell death protein-1, PD-1)." (PMID 33202891, 2020). "Our data shows that granzyme B degraded type IV collagen (C4G) associates with favorable anti-CTLA-4 treatment response in metastatic melanoma patients." (PMID 32998446, 2020). "In contrast, there is a large body of evidence that PD-1 and CTLA-4 inhibitors cause systemic inflammation in metastatic melanoma, including higher circulating levels of IL-1ra, IL-6, and IL-17, which are associated with irAEs such as colitis and dermatitis." (PMID 33302472, 2020). "Immunotherapy targeting T-cell inhibitory receptors, namely programmed cell death-1 (PD-1) and/or cytotoxic T-lymphocyte associated protein-4 (CTLA-4), leads to durable responses in a proportion of patients with advanced metastatic melanoma." (PMID 33202676, 2020). "Ipilimumab, an anti-cytotoxic T-lymphocyte-associated protein 4 (CTLA-4) monoclonal antibody was the first drug to improve survival for metastatic melanoma." (PMID 32894101, 2020). "In a metastatic melanoma cohort, higher burden of copy number loss was observed in non-responders compared to responders on cytotoxic T-lymphocyte associated protein 4 (CTLA-4) blockade." (PMID 32000794, 2020). "Nevertheless, in the last few years, treatment for metastatic melanoma has advanced due to the introduction of cytotoxic T-lymphocyte-associated antigen-4 (CTLA-4) and the programmed cell-death protein 1 (PD-1) checkpoint inhibitors." (PMID 31849977, 2019). "So far, two immune checkpoint blockades, cytotoxic T lymphocyte-associated 4 molecule (CTLA-4) and programmed death 1 (PD-1) have been intensively studied in the treatment of metastatic melanoma." (PMID 31134073, 2019). "In 2011, the breakthrough checkpoint inhibitor (CPI), cytotoxic T-lymphocyte-associated protein-4 antibody (anti-CTLA-4), ipilimumab, was approved for use with metastatic melanoma and is attributed with doubling one- and two-year survival rates." (PMID 31771150, 2019).
metastatic melanoma (continued). "A late relapse patient with metastatic melanoma resistant to CTLA-4 inhibition was found to have biallelic loss of β-2-microglobulin." (PMID 35582566, 2019). "Immune checkpoint inhibitors targeting programmed cell death protein 1 and cytotoxic T-lymphocyte associated protein 4 have improved survival in patients with metastatic melanoma, especially in combination (i.e., ipilimumab-nivolumab)." (PMID 31183226, 2019). "Ipilimumab, an anti-cytotoxic T-lymphocyte associated protein-4 (CTLA-4) monoclonal antibody (mab) was the first ICI to be approved for use in metastatic melanoma." (PMID 35582715, 2019). "While the anti-CTLA-4 drug Ipilimumab acts to upregulate antitumor immunity and shows significant improvement in survival in metastatic melanoma, heterozygous CTLA4 mutations should act similarly." (PMID 30250467, 2018). "In one study of metastatic melanoma patients treated with anti-CTLA-4 (cytotoxic T lymphocyte-associated protein 4; and later with anti-PD-1), early immune infiltration and activation at the tumor site were significantly correlated with treatment response." (PMID 30266097, 2018). "Among these biomarkers, TMB is associated with better clinical outcome in metastatic melanoma treated with anti-CTLA-4 or anti-PD-1 therapy." (PMID 29793878, 2018). "The United States Food and Drug Administration (FDA) first approved ipilimumab (a monoclonal antibody inhibiting cytotoxic T lymphocyte-associated antigen-4 [CTLA-4]) for the treatment of metastatic melanoma in 2011." (PMID 30426287, 2018). "Ipilimumab, a CTLA-4 blocking antibody, has been widely used for the treatment of patients with high risk and metastatic melanoma." (PMID 28344807, 2017). "In these two reports, patients had BRAF wild-type metastatic melanoma managed with a first-line cytotoxic T-lymphocyte-associated protein 4 (CTLA-4) inhibitor (ipilimumab) with maintenance of the graft while on ipilimumab." (PMID 28315636, 2017). "An emerging option for metastatic melanoma with uncommon BRAF mutations is immunotherapy using checkpoint inhibitors such as PD-1 inhibitors or CTLA-4 inhibitors." (PMID 29181212, 2017). "Frequencies of six CTLA-4 gene variants in 173 metastatic melanoma patients and in healthy control subjects." (PMID 28446908, 2017). "The cytotoxic T-lymphocyte-associated protein 4 (CTLA4) antagonist ipilimumab was the first checkpoint inhibitor to demonstrate clinical activity that led to a first approval in metastatic melanoma in 2011." (PMID 28716061, 2017). "More recent efforts to identify an imaging biomarker have reported an elevated spleen-to-liver SUV ratio to be associated with increased overall survival in metastatic melanoma patients treated with anti-CTLA-4 or anti-PD-1 therapy." (PMID 27660712, 2016). "Antibodies targeting PD-1, PD-L1 and CTLA4 have recently shown promise in the context of metastatic melanoma and cancers with mismatch repair deficiency and are now entering trials for breast cancer." (PMID 26729235, 2016). "Immune checkpoint inhibitors targeting cytotoxic T-lymphocyte-associated protein 4 (CTLA-4) and programmed cell death protein 1 (PD-1) have been recently approved for treatment of patients with metastatic melanoma and non-small cell lung cancer (NSCLC)." (PMID 26981243, 2016). "In 2011 the FDA approved anti- cytotoxic T lymphocyte-associated protein 4 (CTLA4) mAb (ipilimumab) for the indication of metastatic melanoma, based on significant improved overall survival in Phase III trials." (PMID 26338962, 2015).